AQR (aquarius intron-binding spliceosomal factor)
Description:
Involved in pre-mRNA splicing as component of the spliceosome. Intron-binding spliceosomal protein required to link pre-mRNA splicing and snoRNP (small nucleolar ribonucleoprotein) biogenesis. Plays a key role in position-dependent assembly of intron-encoded box C/D small snoRNP, splicing being required for snoRNP assembly. May act by helping the folding of the snoRNA sequence. Binds to intron of pre-mRNAs in a sequence-independent manner, contacting the region between snoRNA and the branchpoint of introns (40 nucleotides upstream of the branchpoint) during the late stages of splicing. Has ATP-dependent RNA helicase activity and can unwind double-stranded RNA molecules with a 3' overhang (in vitro).
Synonyms: IBP160; KIAA0560; fSAP164
Tractability: Small molecule: a structure with a bound ligand is known. PROTAC: ubiquitination databases record sites on it; its protein half-life has been measured.
Gene: Protein-coding gene on chromosome 15 (34,851,782 to 34,969,765, reverse strand). Ensembl gene ENSG00000021776.
Subcellular location: Nucleus; Nucleus, nucleoplasm
Subcellular location (Human Protein Atlas): Nucleoplasm
Pathways (Reactome):
DNA Repair: Dual incision in TC-NER; Formation of TC-NER Pre-Incision Complex; Gap-filling DNA repair synthesis and ligation in TC-NER; Transcription-Coupled Nucleotide Excision Repair (TC-NER)
Disease: Dengue Virus-Host Interactions
Metabolism of RNA: mRNA Splicing - Major Pathway
Gene Ontology:
Molecular function: 3'-5' RNA helicase activity; ATP hydrolysis activity; protein binding; RNA binding; single-stranded RNA binding; helicase activity; RNA helicase activity
Biological process: mRNA splicing, via spliceosome
Cellular component: catalytic step 2 spliceosome; membrane; nucleoplasm; nucleus; post-mRNA release spliceosomal complex; post-spliceosomal complex; spliceosomal complex; U2-type catalytic step 1 spliceosome; U2-type catalytic step 2 spliceosome
Genetic constraint (gnomAD): Loss-of-function variants: 39 observed, 123.22 expected, observed/expected ratio (o/e) 0.32, 90% interval 0.24 to 0.41. The upper end of that interval is the gene's LOEUF score, 0.41, which puts it in group 1 of 6, group 1 being the genes least tolerant of losing a copy. Missense variants: 1,014 observed, 1,518.2 expected, observed/expected ratio (o/e) 0.67, 90% interval 0.63 to 0.7. Synonymous variants: 451 observed, 509.6 expected, observed/expected ratio (o/e) 0.89, 90% interval 0.82 to 0.96.
Homologues: Orthologues: chimpanzee AQR (99% identical), macaque AQR (99% identical), pig AQR (97% identical), rabbit AQR (96% identical), rat Aqr (95% identical), mouse Aqr (95% identical), dog AQR (94% identical), tropical clawed frog aqr (80% identical), guinea pig AQR (76% identical), zebrafish aqr (75% identical), Drosophila melanogaster CG31368 (62% identical), Caenorhabditis elegans emb-4 (52% identical). Paralogues in human: ZNFX1 (15% identical), HELZ2 (13% identical), SETX (12% identical), HELZ (12% identical), MOV10L1 (12% identical), DNA2 (11% identical), MOV10 (10% identical), UPF1 (9% identical), IGHMBP2 (9% identical), CT55 (2% identical).
Diseases named in the same sentence as AQR in open-access papers:
AQR is named in the same sentence as 10 diseases in open-access papers, as found by Europe PMC text mining. Sharing a sentence is not in itself a finding about the gene and the disease. The quoted sentences say what the papers report.
Hyperglycemia (1 paper, 2022). An increased concentration of glucose in the blood. "This study aimed to investigate the role of AQR in hyperglycemia-induced senescence and its underlying mechanism." (PMID 35270021, 2022). "Our study demonstrates that AQR/PLAU is a novel but critical signaling axis mediating hyperglycemia-induced cellular senescence that contributes to diabetic vascular complications." (PMID 35270021, 2022).
schizophrenia (1 paper, 2019). A major psychotic disorder characterized by abnormalities in the perception or expression of reality. "RAD51AP1 and AQR are novel interactors of the calcium channel CACNA1C and the nicotinic receptor CHRNA7 respectively in the schizophrenia interactome, found to have an anti-correlated expression in schizophrenia and acetazolamide treatment." (PMID 31481665, 2019).
genetic diseases (1 paper, 2024). "We identified four high-impact variants in four candidate novel genes (ZBTB38, AQR, APBA1, and TXLNA) not implicated before in NDD or genetic diseases in four probands/families." (PMID 38300321, 2024).
neurodegenerative disease (1 paper, 2024). A disorder of the central nervous system characterized by gradual and progressive loss of neural tissue and neurologic function. "Our results found AQR, ZNF587B, CRP, and PAGIn have been accumulated in AD patients as well as been reported associated with neurodegenerative diseases, while their relationship with AD has not been thoroughly examined." (PMID 38605603, 2024).
AQR also shares sentences with these, for which no sentence is quoted: cancer (2 papers); acute coronary syndrome (1); gastric cancer (1); heart failure (1); infection (1); lung carcinoma (1).